CCND1 (cyclin D1)
Diseases named in the same sentence as CCND1 in open-access papers (continued):
Sharing a sentence is not in itself a finding about the gene and the disease.
tumor (continued). "We also support a new mechanism of c-Myc overexpression in TNBC: 66CTG stabilized the c-Myc protein by supplying itself to FBW7α during the late G1 phase, thereby increasing Cyclin D1 transcription, promoting TNBC cell proliferation and tumor growth." (PMID 40628713, 2025). "Here, we found that 66CTG stabilized c-Myc by competitive interaction with FBW7α, which further enhanced the Cyclin D1 transcription and promoted TNBC cell proliferation and tumor growth." (PMID 40628713, 2025). "Prior work has demonstrated the tumor-suppressive effect of miR-138-5p through regulation of EZH2 and CCND1 in other cancers." (PMID 40869426, 2025). "Inhibition of the activity of the aromatase enzyme, cyclin D1, CDK4, Bcl-xL, and pS2, while increasing the expression of CCAAT/C/EBP, pERK-1&-2, and p57Kip2 that results in decrease the tumour growth." (PMID 40427522, 2025). "In summary, our study delineates a previously unrecognized tumor-suppressive pathway in HCC proliferation, linking PPP1R12B to cell cycle control via PAK2/β-catenin/Cyclin D1 axis." (PMID 40612101, 2025). "We then infected cultures of the patient’s tumor cells with recombinant lentiviruses carrying the CDK4R24C, cyclin D1 and TERT genes, and continued to grow them under standard cell culture conditions." (PMID 39878900, 2025). "Molecular investigations reveal that let‐7a exerts its tumor‐suppressive effects by targeting multiple oncogenes, including high mobility group AT‐hook 2 (HMGA2) and cyclin D1 (CCND1)." (PMID 40452566, 2025). "SIX1 overexpression upregulates cyclin D1, cyclin E, ERK, and AKT expression, enhancing tumor growth and colony formation capacity." (PMID 40746599, 2025). "Immunohistochemistry (IHC) staining and western blotting of tumor xenografts 5 days post treatment confirmed significant downregulation of p300/CBP, AR, PSA, MYC, Ki67, CCND1, NKX3-1, CITED2, H3K27ac and H2BK20ac." (PMID 41044247, 2025). "These signaling events are pivotal in upregulating the expression of genes like cyclin-D1, VEGF, c-myc, and Bcl-xL that fosters immune regulatory mechanisms and supports tumor expansion." (PMID 41376623, 2025). "The overexpression of SKA3 activates the PI3K/AKT signaling pathway, increases the levels of p-AKT, cyclin D1, CDK4, CDK2, p-Rb and E2F1, promotes the proliferation and migration of HeLa cells, and accelerates tumor growth." (PMID 40746599, 2025). "The tumor cells frequently express cytokeratin AE1/AE3, low-molecular-weight cytokeratin, vimentin, cyclin D1, hypoxia-inducible factors (HIF), and VEGF." (PMID 41497945, 2025). "Western blotting analysis of tumor tissues found that EVO remarkably reduced the expression levels of proteins β-catenin, c-MYC, Cyclin D1, and ASS1 in subcutaneous CRC syngeneic tumor allografts." (PMID 41304979, 2025). "Studies documenting relapse rates reported correlations between lower disease-free survival and increased Cyclin D1 or VEGF expression, and between increased tumor recurrence and decreased Cornulin expression or increased HRAS expression." (PMID 41465166, 2025). "Cyclin-d1 also participates in pathways that maintain CSC stemness, contributing to therapy resistance and tumor relapse." (PMID 40011711, 2025).
tumor (continued). "As a consequence, the addition of gedatolisib to fulvestrant and/or palbociclib reduced cyclin D1/CDK-RB pathway reactivation and cell cycle recovery, resulting in the long-term inhibition of colony expansion in vitro and tumor growth inhibition in vivo." (PMID 40565304, 2025). "Immunohistochemistry (IHC) staining of tumor tissue sections further revealed that cotreatment with ASO-circFOXK2 and tamoxifen had synergistic effects in reducing the expression of Ki67 and CCND1, as well as the abundance of p-RB." (PMID 40233410, 2025). "When cyclin D1 expression is reduced, palbociclib binds more strongly to CDK4/6, resulting in a more effective inhibition of tumor cell proliferation." (PMID 40040723, 2025). "HE, IHC staining and WB showed the expression of MAT1A, CCND1, proliferation marker Ki67 and glycolytic marker (ALDOC, HK2) in tumor tissues, emphasizing the regulation of MAT1A and CCND1 on NSCLC cells." (PMID 39438468, 2024). "In CRC, it is considered a tumor-suppressive miRNA through multiple mechanisms such as targeting of pro-metastatic (NOB1, ADAM-17, ZEB1) and proliferative (CCND1, FGF) elements." (PMID 39057062, 2024). "Because cyclin D1 overexpression has a protective effect on bipolar spindle integrity under compressive force, we propose that it helps to prevent multipolar anaphases and speculate that it may allow cells to continue proliferating under compressive stress in the tumor context." (PMID 38478555, 2024). "CDK4 and CDK6 play a key role in mammalian cell proliferation by working in complex with CCND1 to phosphorylate and inhibit RB1 tumor-suppressor activity during early G1 phase." (PMID 38507413, 2024). "The multivariate analysis included tumour stage and CDK4, CDK6, CDK2, cyclin D1, cyclin E1, RB1 and pRB1 protein expression." (PMID 38612869, 2024). "Immunohistochemical examination showed expression by the tumor cells of antibodies to CD20, CD5, Bcl2, and cyclin D1." (PMID 38698463, 2024). "The cell cycle in tumors is modulated by c-Myc, which regulates the expression of downstream target molecules, including cyclin D1/2, cyclin E1, CDK4, cdc25A, and E2F1, and promotes tumor growth." (PMID 39085875, 2024). "Glabridin downregulates Wnt1, β-catenin, and downstream proteins Cyclin D1, MMP-2, and Survivin, inhibiting the tumor cell cycle." (PMID 39723390, 2024). "This class is known as a tumor suppressor and works by targeting the BCL2,MCL1, CCND1, and WNT3A genes." (PMID 38530760, 2024). "The expression levels of gp130 and the downstream targets c-Myc, cyclin D1 and Bcl-xL and the p-STAT3/STAT3 ratio were lower in the ART1-sh-transplanted tumours than in the NC tumours (P < 0.01)." (PMID 38504172, 2024). "This signature, comprising TRP53BP1, P21, BAX, CYCLIN D1, OCT-4, and NANOG, appears to influence tumor response to radiation." (PMID 39594660, 2024). "The tumor morphology was suggestive of HGESS with variable expression of desmin, ER, PR, AE1/3 and cyclin D1." (PMID 39196362, 2024). "For example, CCND1 and CTTN showed amplification in more than 9 tumor foci, while CDKN2A and CDKN2B exhibited deletion in more than 6 tumor foci." (PMID 38956687, 2024). "It is also known that p16 is a tumor suppressor protein that acts by inhibiting the cyclin D1/CDK4 complex, favoring the survival of tumor cells." (PMID 38742684, 2024). "FGFR1 alterations promote tumor invasion through EMT mechanisms, while CCND1 regulates cell cycle progression through cyclin pathways." (PMID 39410541, 2024). "In contrast to NDRG1, NDRG2 acts as a tumor suppressor, inhibiting proliferation and cell survival via regulations of MAPK/STAT3, cyclin-D1, β-catenin, NF-κB, E-cadherin, and other signaling pathways." (PMID 38611020, 2024).
tumor (continued). "Cyclin D1 (CCDN1) functions as a molecular link connecting cell cycle regulation, adhesion, invasion, and the interplay between tumor, stroma, and the immune system in cancer." (PMID 38892366, 2024). "Consistent with our in vitro findings, immunohistochemistry (IHC) staining and western blotting of tumor xenografts five days post treatment confirmed significant downregulation of p300/CBP, AR, PSA, MYC, Ki67, CCND1, NKX3–1, CITED2, H3K27ac, and H2BK20ac." (PMID 38586029, 2024). "They found that downregulation of mitochondrial function negatively affects tumor progression and LNM through the PI3K/Akt/FoxO1/Cyclin D1 pathway." (PMID 39179991, 2024). "POU4F1 is necessary for the tumor growth and malignant phenotypes of BLBC through regulating G1/S transition by direct binding at the promoter of CDK2 and CCND1." (PMID 38491910, 2024). "Early studies showed that CCND1 and CDK6 are activated in tumor cells and their expressions are upregulated." (PMID 38711992, 2024). "The expression of HLA in CCND1-amplified tumor cells was upregulated by CDK4/6 inhibitors, which also activated the expression of retroviral elements in tumor cells treated with Abemaciclib." (PMID 39544302, 2024). "Higher expression of CCND1 and CD44 in p16-/HPV- tumours relative to p16+/HPV+ aligns with their poorer prognosis." (PMID 39328208, 2024). "Cyclin D1/CDK4 acts as a key effector of AKT, mediating resistance to HER2-directed therapies, and CDK4/6 inhibitors can resensitize resistant tumor cells." (PMID 39769140, 2024). "Tumor sequencing revealed LOH in CHEK2 and PALB2, as well as CCND1,FGFR1, GPR124, ZNF217, ZNF703, and PTPN1 amplifications." (PMID 38091153, 2024). "In tumor cells, PTEN acts as an anti-proliferative agent by inhibiting cyclin D1 transcription through AKT inactivation and increasing lipid phosphatase activity in the cytoplasm, resulting in elevated p27 expression." (PMID 39298504, 2024). "Upon activation, phosphorylated STAT3 translocates into the nucleus and promotes the expression of target genes such as cyclin D1, survivin, Bcl-xL, and MCL-1, which are involved in tumor cell proliferation, angiogenesis, and immune evasion." (PMID 39123466, 2024). "Because USP9X affects cell migration and angiogenesis by elevating CCND1-mediated SOX11 expression, USP9X suppression leads to the downregulation of USP9X protein levels in Z-138 and Jeko-1 cell lines and inhibits tumor development in mice in vivo." (PMID 39664521, 2024). "Circulating tumor DNA testing at the onset of the second episode of DIC revealed high levels of androgen receptor, CCND1, and PDGFRA gene amplification." (PMID 39764338, 2024). "The high protein levels of CCND1 and RB1 hyperphosphorylation in long-term FLCN knockdown HK2 tumor spheroids likely contributes to their observed tumorigenicity." (PMID 38978568, 2024). "The inhibition of tumor growth by NSC311152 in vivo was mediated by the reduced protein expression of RET, c-Myc, Bcl-2 and cyclin D1 in tumor tissues evaluated using western blotting." (PMID 38791433, 2024). "In agreement with our flow cytometry findings, we found that DYRK1A inhibition leads to increase in expression of G1/S regulators (i.e. Cyclin D1, and CDK4) and a decrease in expression of CENP-A in tumor samples." (PMID 38839871, 2024).
tumor (continued). "Our findings indicate that this compound can effectively disrupt the interactions between CCND1 and CDK4, leading to inhibition of tumor cell proliferation." (PMID 38957406, 2024). "In two patients with HG-ESS with breast metastasis, both tumor cells showed diffuse positive staining for CD10 and cyclin D1." (PMID 39474112, 2024). "Nulliparity was also associated with specific characteristics of breast cancer, including larger tumour size (> 20 mm), high levels of Ki67, high levels of cyclin D1, grade III tumours, and HER2-positive tumours." (PMID 39096427, 2024). "It acts by targeting Cyclin D1 and the metalloproteinase MMP-9, decreasing tumor proliferation and invasiveness." (PMID 39057062, 2024). "In concordance, HACE1 suppressed the expression of CCND1, Bcl-2, and MMP2 in tumor tissue, with EHop-016 intensifying the inhibitory effects on these proteins." (PMID 38706891, 2024). "As Cyclin D1 is crucial for cell cycle advancement from G1 to S phase, its downregulation following PDT contributes to the cessation of tumor growth." (PMID 39682631, 2024). "While CCND1 and FOXI1 were enriched in the nuclei, GPNMB showed a homogeneous and moderate/strong expression within the cytoplasmic compartment of the chRCC tumor cells, and MAPRE3 protein showed a predominant membranous expression pattern in RO." (PMID 38703764, 2024). "CCND1, AKT1 and CD44 were all expressed at significantly higher levels in the tumour compartment of p16-/HPV- relative to p16+/HPV+ OPC, with CCND1 also being upregulated in the stromal compartment." (PMID 39328208, 2024). "In general, SHCBP1 can promote tumor growth and invasion in GC by regulating the CDK4-cyclin D1 cascade and caspase-3 and caspase-PARP-dependent apoptosis pathways." (PMID 36920183, 2023). "The tumor cells of HGESS were often smaller with irregular or tongue-like invasion into the myometrium, and CCND1 and BCOR were often positive on IHC." (PMID 36994196, 2023). "Overexpression of cortactin could contribute to the emergence of invasive tumor phenotypes in a variety of ways, including enhanced actin polymerization, down-regulated epidermal growth factor receptor, and molecule interactions between cyclin D1 and CD44 proteins." (PMID 38077360, 2023). "The tumor cells were stained positive for CD34, P16, SMARCA4, and INI1 and scattered weak-positive for CCND1." (PMID 36994196, 2023). "CCND1 forms complexes with CDK4 or CDK6 as a regulator of CDK kinases, and its tumor-promoting role has been intensively investigated in human cancers." (PMID 37770914, 2023). "Additional research has shown that arctiin is able to suppress inflammation, fibrosis, and the migration of tumor cells by inhibiting STAT3, TGF-β1, TLR4, NLRP3, VEGF, and cyclin D1." (PMID 37701157, 2023). "In contrast, ASPA knockdown resulted in increased tumor weights and up-regulated expression of PCNA, cyclin D1, N-cadherin, and MMP9 (P < 0.05 or P < 0.01), concomitant with the inhibition of E-cadherin expression (P < 0.01)." (PMID 37271807, 2023). "MiR-449b inhibits the expression of cyclin D1 and E2F3 by binding to their 3′-UTRs, which reduces the growth of colon cancer stem cells and has tumor-suppressive effects." (PMID 37240281, 2023). "Immunohistochemical analyses of harvested tumours confirmed downregulation of NCP26 targets, including MYC, CCND1 and TCF3, and ISR engagement, evidenced by induction of p-GCN2 and DDIT3." (PMID 36631435, 2023). "Results showed that the high value of regulatory potential between MFAP5 and some of its top predicted NOTCH1/WNT pathway target genes (CCND1, HES1, MYC, RBPJ, NOTCH1, CCN3, CTNNB1 and SOX17) in inferring signaling paths in tumour tissues." (PMID 36855786, 2023).
tumor (continued). "In addition, a tumor-burden mice model by cell transplantation further demonstrated the promotion of tumor growth by pMX-CCAT2 in vivo, which was associated with increased levels of cell proliferation factors (Ki67 and CCND1) and cell stemness genes (h-TERT, NANOG, SOX2, KLF4 and OCT4)." (PMID 36672487, 2023). "Tumor volume and TLR1, BCL-2, Cyclin D1 and survivin protein levels were significantly reduced in the combined treatment group with miR-15a + RT or miR16 + RT compared to control or single modality treatment." (PMID 37112730, 2023). "In tumor tissue from BC patients, NF-kB, STAT3 and their target genes (i.e., cyclin-D1, VEGF-A, and TGFβ1) have been found to be activated in comparison to healthy tissue, suggesting that chronic inflammation can promote tumor development." (PMID 36614308, 2023). "Let-7 has been shown to inhibit the cell cycle regulators cyclin D1, cyclin D3, cyclin A and CDK4 and stop tumour growth." (PMID 38357103, 2023). "Based on the TCGA database, we found that CCND1 and NRP2 mRNA expression was significantly increased in the HCC compared with adjacent non-tumor." (PMID 37928273, 2023). "Under hypoxic conditions, CD44-ICD binds to HIF-2α and activates HIF-2α expression, which further activates HIF-2α target genes, including cyclin D1, Nanog, Oct4, Sox2, and OPN, resulting in the promotion of tumor proliferation and stemness of GSCs." (PMID 37835592, 2023). "Multiple studies have demonstrated that STAT3 plays a crucial role in regulating various target genes during tumor development and progression, including VEGF, cyclin D1, and Bcl-xL." (PMID 37701157, 2023). "The tumor samples were used to evaluate the expression of HIF-1α, Nrf2, HO-1, cMyc, cyclin D1, mTOR, and STAT3." (PMID 37465088, 2023). "Cyclin D1 expression was assessed in fourteen samples from this group (including eleven GI, one GII, and two GIII tumors) and additional tumor samples." (PMID 37686289, 2023). "Together with their promising suppressive effects on cyclin D1 and c-Myc expression, there exists a considerable potential of iodidogold(I)–NHC complexes as new candidates for the treatment of problematic tumor diseases such as EAC." (PMID 36982817, 2023). "An additional mediator of let-7-driven caspase 3 upregulation is cyclin D1 (CCND1), which phosphorylates and thereby inactivates retinoblastoma (Rb) protein, a tumor suppressor that inhibits G1-S phase progression." (PMID 37370851, 2023). "EDX suppressed elevated plasma levels of IL-6, MMP-2, TF, and PAI-1 and elevated tumor tissue levels of PAR2, STAT3, cyclin D1, and Ki67 in Colon26-inoculated mice." (PMID 36751299, 2023). "However, this association could not be confirmed using association analyses of germline CCND1 variants, CCND1 tumour gene expression, and recurrence-free survival in additional independent cohorts." (PMID 38994482, 2023). "This list of driver genes, however, was not particularly comprehensive, because other studies have also identified a broad spectrum of gene abnormalities in OSCC that are likely to contribute to tumour development and progression (FAT1, EGFR, CCND1)." (PMID 36671795, 2023). "Through direct regulation of cyclin D1 and E2F1 expression, ISX regulated the proliferation of tumour cells and their transforming activity." (PMID 37349365, 2023).